YOD1 (YOD1 deubiquitinase)
Description:
Hydrolase that can remove conjugated ubiquitin from proteins and participates in endoplasmic reticulum-associated degradation (ERAD) for misfolded lumenal proteins. May act by triming the ubiquitin chain on the associated substrate to facilitate their threading through the VCP/p97 pore. Ubiquitin moieties on substrates may present a steric impediment to the threading process when the substrate is transferred to the VCP pore and threaded through VCP's axial channel. Mediates deubiquitination of 'Lys-27'-, 'Lys-29'- and 'Lys-33'-linked polyubiquitin chains. Also able to hydrolyze 'Lys-11'-linked ubiquitin chains. Cleaves both polyubiquitin and di-ubiquitin. May play a role in macroautophagy, regulating for instance the clearance of damaged lysosomes. May recruit PLAA, UBXN6 and VCP to damaged lysosome membranes decorated with K48-linked ubiquitin chains and remove these chains allowing autophagosome formation.
Synonyms: HIN-7; DUBA8; OTUD2; PRO0907; DKFZp451J1719; DUBA-8
Tractability: Antibody: the Human Protein Atlas places it where antibodies can reach. PROTAC: ubiquitination databases record sites on it.
Target class: Enzyme; Hydrolase
Gene: Protein-coding gene on chromosome 1 (207,043,849 to 207,052,980, reverse strand). Ensembl gene ENSG00000180667.
Subcellular location: Cytoplasm
Subcellular location (Human Protein Atlas): Cytosol; Nucleoplasm; Plasma membrane
Pathways (Reactome):
Metabolism of proteins: Ovarian tumor domain proteases
Gene Ontology:
Molecular function: cysteine-type deubiquitinase activity; K48-linked deubiquitinase activity; protein binding; ubiquitin protein ligase binding; deubiquitinase activity; K63-linked deubiquitinase activity; catalytic activity
Biological process: endoplasmic reticulum unfolded protein response; ERAD pathway; macroautophagy; negative regulation of retrograde protein transport, ER to cytosol; protein K11-linked deubiquitination; protein K27-linked deubiquitination; protein K29-linked deubiquitination; protein K33-linked deubiquitination; protein K48-linked deubiquitination; protein K63-linked deubiquitination
Cellular component: cytoplasm; cytosol; nucleoplasm; plasma membrane; nucleus
Genetic constraint (gnomAD): Loss-of-function variants: 17 observed, 25.24 expected, observed/expected ratio (o/e) 0.67, 90% interval 0.46 to 1.01. The upper end of that interval is the gene's LOEUF score, 1.01, which puts it in group 4 of 6, group 1 being the genes least tolerant of losing a copy. Missense variants: 413 observed, 461.48 expected, observed/expected ratio (o/e) 0.89, 90% interval 0.82 to 0.97. Synonymous variants: 191 observed, 177.66 expected, observed/expected ratio (o/e) 1.08, 90% interval 0.95 to 1.21.
Homologues: Orthologues: chimpanzee YOD1 (99% identical), macaque YOD1 (98% identical), rabbit YOD1 (93% identical), guinea pig YOD1 (91% identical), dog YOD1 (90% identical), mouse Yod1 (87% identical), pig YOD1 (81% identical), zebrafish yod1 (62% identical), tropical clawed frog yod1 (61% identical), Drosophila melanogaster Yod1 (41% identical).
Diseases named in the same sentence as YOD1 in open-access papers:
YOD1 is named in the same sentence as 63 diseases in open-access papers, as found by Europe PMC text mining. Sharing a sentence is not in itself a finding about the gene and the disease. The quoted sentences say what the papers report.
ovarian tumor (10 papers, 2014 to 2024). "YOD1 is a deubiquitinating enzyme (DUB) in the ovarian tumor (OTU) family that removes ubiquitin residues from poly-ubiquitinated proteins." (PMID 24722419, 2014). "YOD1 is a highly conserved deubiquitinating enzyme of ovarian tumor family." (PMID 38042492, 2023). "Furthermore, a co-IP assay between USP21 and deletion forms of YOD1 revealed that the ubiquitin regulatory X (UBX), ovarian tumor (OTU) domain of YOD1 are required for the interaction between USP21." (PMID 37743467, 2023). "Here, we report on the identification of the OTU (ovarian tumor) DUB family member YOD1 (homolog of yeast OTU1; OTUD2, DUBA8) as a new interactor of TRAF6." (PMID 28244869, 2017). "Thus, Pearson correlation analysis between the expression level of B4GALT5 and OTU (ovarian tumour) family deubiquitinases (OTUB1, OTUB2, OTUD1, YOD1, OTUD3, OTUD4, OTUD7B) was performed." (PMID 36611197, 2023).
hepatocellular carcinoma (6 papers, 2021 to 2025). A malignant tumor that arises from hepatocytes. "For example, in a hepatocellular carcinoma (HCC) murine model, M2 macrophage‐derived extracellular vesicles encapsulating miR‐21‐5p promoted CD8+ T‐cell exhaustion in the TIME by targeting YOD1 and activating the Yes‐associated protein (YAP)/β‐catenin pathway." (PMID 41346571, 2025). "YOD1 regulates the stability of PML/RARα, CDK1, and ITCH, promoting malignant phenotypes in acute promyelocytic leukemia, triple-negative breast cancer, and hepatocellular carcinoma, respectively." (PMID 40274778, 2025). "Another study found that M2 macrophages-derived EVs carried miR-21-5p entered into CD8 T cells to inhibit YOD1 expression and activate YAP/β-catenin pathway, thus promoting CD8 T cell depletion in hepatocellular carcinoma, which provided new insights into hepatocellular carcinoma immunotherapy." (PMID 37400770, 2023).
pancreatic cancer (6 papers, 2022 to 2025). "YOD1, an important member of this subfamily, has emerged as a key player in multiple malignancies, including liver and pancreatic cancers, where it regulates pathways such as the Hippo signaling axis to promote tumor cell proliferation." (PMID 40274778, 2025). "Cox analysis showed that high YOD1 expression is an independent prognostic factor of pancreatic cancer." (PMID 35642058, 2022). "In the GEO and TCGA databases, YOD1 mRNA expression is significantly up regulated in a variety of human pancreatic cancer tissues." (PMID 35642058, 2022). "The immunohistochemistry (IHC) results showed that the protein expression level of YOD1 in pancreatic cancer tissue was higher than that in neighboring non-pancreatic cancer tissues (P < 0.001)." (PMID 35642058, 2022). "Survival analysis showed that the up regulation of YOD1 can predict poor prognosis of pancreatic cancer." (PMID 35642058, 2022). "Additionally, YOD1 correlates with poor patient outcomes in gallbladder cancer, osteosarcoma, and pancreatic cancer." (PMID 40274778, 2025). "Moreover, aberrant expression of YOD1 is able to accelerate the progression of pancreatic carcinoma." (PMID 37573347, 2023). "However, the expression level, prognostic effect and biological functional mechanism of YOD1 in pancreatic cancer are still unclear." (PMID 35642058, 2022). "It is proved that YOD1 may regulate the occurrence, development and prognosis of pancreatic cancer through these two key aspects." (PMID 35642058, 2022). "Our results indicate that YOD1 may be a useful biomarker for the prognosis of human pancreatic cancer, and it may also be a potential molecular target for the diagnosis and treatment of pancreatic cancer." (PMID 35642058, 2022). "It maybe can be speculated that YOD1 can serve as a new way to improve the effectiveness of pancreatic cancer immunotherapy." (PMID 35642058, 2022). "In addition, we found that YOD1 expression is negatively correlated with the infiltration level of CD8 + T cells, macrophages, neutrophils and dendritic cells (DC) in pancreatic cancer." (PMID 35642058, 2022).
gallbladder cancer (5 papers, 2021 to 2025). "It has previously been reported that YOD1 is closely associated with multiple tumors, including liver cancer, gallbladder cancer, pancreatic adenocarcinoma, acute promyelocytic leukemia, osteosarcoma, and ovarian cancer." (PMID 37573347, 2023). "Additionally, lncRNA FIRRE encourages the progression of gallbladder carcinoma through mediation of YOD1 expression when it functions as a miR-520a-3p sponge." (PMID 37573347, 2023). "By sponging miR-520a-3p and regulating YOD1, lncRNA FIRRE function as a new mediator in gallbladder cancer progression." (PMID 35669241, 2022).
acute promyelocytic leukemia (4 papers, 2023 to 2025). An aggressive form of acute myeloid leukemia (AML), characterized by arrest of leukocyte differentiation at the promyelocyte stage, due to a specific chromosomal translocation t(15;17) in myeloid cells. "The small molecule G5 has been reported to pharmacologically inhibit YOD1 and consequently exert antiacute promyelocytic leukemia effects." (PMID 40561034, 2025). "However, it is interesting to note that a recent study demonstrated the stabilizing effects of YOD1 on oncogenic PML/RARα frequently found in promyelocytic leukemia (APL)." (PMID 37454155, 2023). "In acute promyelocytic leukemia (APL), YOD1 raises the PML/RARa oncoprotein’s stability; therefore, a selective YOD1 inhibitor named ubiquitin isopeptidase inhibitor I (G5) may offer the chance to treat APL which is resistant to treatment." (PMID 37573347, 2023).
cervical cancer (4 papers, 2018 to 2025). A primary or metastatic malignant neoplasm involving the cervix. "Furthermore, YOD1 reverses the proliferative effects of upregulated miR-373 in cervical cancer cells." (PMID 40274778, 2025). "However, a recent study showed that downregulation of YOD1 may promote cell proliferation in cervical cancer cells." (PMID 30345304, 2018).
liver cancer (4 papers, 2018 to 2023). An epithelial or non-epithelial malignant neoplasm that arises from the liver. "Studies have confirmed that under high cell density, the progression of liver cancer can be inhibited by the miR-21 − YOD1 − ITCH − LATS signal axis." (PMID 35642058, 2022). "Therefore, an increased level of YOD1 might play a tumorigenic role in liver cancer by suppressing Hippo activity, and its inhibitor could be used as a therapeutic tool to reactivate Hippo signaling in liver cancer." (PMID 33158118, 2020). "Thus, YOD1 inhibitors may potentially be assessed as a therapeutic tool to reactivate Hippo signaling in liver cancer." (PMID 29673168, 2018).
breast carcinoma (3 papers, 2023 to 2025). "In breast cancer (BC), OTUD5, YOD1, OTUD6A, OTUD7B, ZRANB1, and TNFAIP3 were characterized as carcinogenic drivers." (PMID 40469292, 2025). "In breast cancer, for instance, OTUB1, YOD1, OTUD5, OTULIN, TNFAIP3, and ZRANB1 drove chemoresistance, whereas OTUD1 and OTUD3 were sensitized to chemotherapy." (PMID 40469292, 2025). "The publicly available TCGA database of breast cancer data was used to analyze the OTUD deubiquitinating family members that were correlated with survival of breast cancer and ovarian tumor domain-containing 2 (OTUD-2), or YOD1 was identified." (PMID 37667382, 2023).
depression (3 papers, 2020 to 2024). "Together, these suggest that YOD1 is associated with depression perhaps via influencing the inflammatory responses." (PMID 32733030, 2020). "The top three genes of the module, YOD1, RBX1, and LEPR, have been shown previously to be associated with neurodegenerative diseases, bipolar disorder, and depression." (PMID 38726387, 2024).
glioma (3 papers, 2023 to 2024). A benign or malignant brain and spinal cord tumor that arises from glial cells (astrocytes, oligodendrocytes, ependymal cells). "For example, miR-190a-3p exhibited elevated levels in glioma, where it stimulated proliferation and migration by targeting YOD1." (PMID 38500077, 2024). "Blocking miR-190a-3p or the overexpression of its target OTUD2/YOD1 attenuated the proliferation and migration of glioma cells." (PMID 37892185, 2023). "In glioma, OTUD2/YOD1 has been identified as a target of miR-190a-3p." (PMID 37892185, 2023).
Huntington disease (3 papers, 2020 to 2023). Huntington disease (HD) is a rare neurodegenerative disorder of the central nervous system characterized by unwanted choreatic movements, behavioral and psychiatric disturbances and dementia. "Moreover, YOD1 level upregulation was reported to be induced by neurogenic proteins, causing Huntington’s disease and PD." (PMID 34956196, 2021). "At last, previous studies suggest that YOD1 contributes to pathogenesis of neurodegenerative disease like Huntington disease and Parkinson’s disease." (PMID 32733030, 2020).
ovarian carcinoma (3 papers, 2022 to 2023). A malignant neoplasm originating from the surface ovarian epithelium. "According to one study, MiR-4429 inhibits the growth of ovarian carcinoma by targeting YOD1." (PMID 37573347, 2023).
triple-negative breast carcinoma (3 papers, 2023 to 2025). An invasive breast carcinoma which is negative for expression of estrogen receptor (ER), progesterone receptor (PR), and human epidermal growth factor receptor 2 (HER2). "It was found that YOD1 was significantly upregulated in TNBC tissues compared with non-triple-negative breast cancer (NTNBC), which was positively correlated with poor survival in TNBC patients." (PMID 37667382, 2023). "For example, YOD1 stabilizes CDK1 through deubiquitination, promoting tumorigenesis in triple-negative breast cancer." (PMID 40534847, 2025).
viral infection (3 papers, 2020 to 2024). "Liu and colleagues reported YOD1-mediated K63-linked deubiquitination could activate an innate antiviral immune response against viral infection, and the aggregation of MAVS." (PMID 33343629, 2020). "YOD1 is a deubiquitinase of the OTU (otubain) protein family, which has been implicated in the occurrence and progression of viral infectious diseases and a wide spectrum of cancer through removing ubiquitin chains and regulating protein degradation." (PMID 38789414, 2024). "After viral infection, OTUD2 (also known as YOD1) interacts with MAVS through its UBX and Znf domains at the mitochondria, followed by the cleavage the K63-linked ubiquitin chains of MAVS that induced the abrogation of MAVS oligomerization to attenuate the IFN production." (PMID 35008917, 2022).
cleft lip (2 papers, 2018 to 2022). Congenital defect in the upper lip where the maxillary prominence fails to merge with the merged medial nasal prominences. "We have identified a gene YOD1 encoding deubiquitinating enzyme (DUB) responsible for nonsyndromic cleft lip with or without cleft palate (NSCL/P)." (PMID 30345304, 2018).
cleft palate (2 papers, 2018 to 2020). Cleft palate is a fissure type embryopathy that affects the soft and hard palate to varying degrees. "Previous studies suggested that YOD1 correlated with another congenital malformed disease: nonsyndromic cleft lip, with or without cleft palate (NSCL/P)." (PMID 33343629, 2020).
coronary artery disease (2 papers, 2019 to 2021). "For example, circ-YOD1 was considered as a biomarker for coronary artery disease, and circDLPAG4 was identified as a potential therapeutic target for myocardial ischemia." (PMID 33869778, 2021).
prostate carcinoma (2 papers, 2024 to 2026). A carcinoma that arises from epithelial cells of the prostate gland. "A study by Chen indicated that enzalutamide resistance-associated lncRNA NONHSAT-210528 can function as a competitive endogenous RNA (ceRNA) that promotes prostate cancer cell invasion and drug resistance through the miR-21-5p/YOD1 signaling pathway." (PMID 39655078, 2024). "Among protein nodes, QKI, YOD1, and TBL1XR1 were the most connected, with 19, 15, and 14 edges, respectively (which ranks potential biomarkers and their impacts in prostate cancer)." (PMID 41598250, 2026).
Sepsis (2 papers, 2024 to 2025). Sepsis is defined as life-threatening organ dysfunction caused by a dysregulated host response to infection. "Research findings demonstrate a significant increase in YOD1 expression during sepsis, which correlates with macroautophagy." (PMID 40867920, 2025). "Deubiquitinase YOD1 is involved in the process of ERAD and has been recognized as a potential diagnostic and prognostic biomarker for sepsis, likely influencing immune processes associated with the condition." (PMID 40867920, 2025). "In summary, our study revealed one of the essential and original mechanisms by which YOD1 promoted sepsis-induced DIC, and proposed YOD1 as a priming therapeutic target for NLRP3-inflammasome dysregulation-mediated disorders." (PMID 38789414, 2024). "YOD1 also exhibited increased levels in the murine model of sepsis, consistent with the findings of the current study, and was demonstrated to effectively diagnose sepsis and predict the prognosis." (PMID 40867920, 2025). "The administration of MCC950, a highly potent and specific inhibitor of NLRP3, effectively blocked YOD1-mediated coagulation in MRSA-induced sepsis, thereby supporting the role of YOD1 in regulating NLRP3 inflammasome-dependent coagulation during MRSA-induced disseminated intravascular coagulation." (PMID 40867920, 2025). "Moreover, YOD1 provides a defense against methicillin-resistant Staphylococcus aureus (MRSA) sepsis." (PMID 40867920, 2025). "Furthermore, a positive correlation was observed between cAMP responsive element binding protein 3 like 2 (CREB3L2) and BCL2L1, as well as between the expressions of USP14 and YOD1 deubiquitinase (YOD1) in sepsis." (PMID 40867920, 2025). "Taken together, these results illustrated that YOD1 alleviated coagulation in sepsis." (PMID 38789414, 2024). "Notably, we found that the number of MRSA in their blood and major organs from mice with Yod1 gene deletion was much higher than those in WT mice with sepsis." (PMID 38789414, 2024). "In addition, YOD1-mediated coagulation in MRSA-induced sepsis was blocked by the administration of MCC950, a highly potent and specific inhibitor of NLRP3, which supported that YOD1-regulated NLRP3 inflammasome-dependent coagulation in the process of MRSA-induced DIC." (PMID 38789414, 2024). "Compared with MRSA-induced sepsis in WT mice, the APTT and D-Dimer were increased markedly in Yod1−/− mice, while the platelets were decreased." (PMID 38789414, 2024). "Here, we identified the deubiquitinase YOD1, which played a vital role in regulating coagulation in a NLRP3 inflammasome-dependent manner in sepsis induced by methicillin-resistant Staphylococcus aureus (MRSA)." (PMID 38789414, 2024). "To explore the potential function of YOD1 in the progression of sepsis-induced DIC in vivo, we generated Yod1-knockout mice and constructed a sepsis mouse model by intravenous injection of MRSA." (PMID 38789414, 2024). "Thus, our findings for the first time revealed the immunological role of YOD1 in regulating NLRP3 inflammasome activation and coagulation in MRSA sepsis, and also provided a potential therapeutic target to treat sepsis-induced DIC." (PMID 38789414, 2024).
breast tumor (1 paper, 2023). "Next, we analyzed YOD1 and CDK1 expressions by Western Blotting in the tumor tissues and found that CDK1 expression was downregulated in the tumor tissues of breast tumor-bearing mice with YOD1 knockdown." (PMID 37667382, 2023).